NCOR2 (nuclear receptor corepressor 2)
Description:
Transcriptional corepressor that mediates the transcriptional repression activity of some nuclear receptors by promoting chromatin condensation, thus preventing access of the basal transcription. Acts by recruiting chromatin modifiers, such as histone deacetylases HDAC1, HDAC2 and HDAC3. Required to activate the histone deacetylase activity of HDAC3. Involved in the regulation BCL6-dependent of the germinal center (GC) reactions, mainly through the control of the GC B-cells proliferation and survival. Recruited by ZBTB7A to the androgen response elements/ARE on target genes, negatively regulates androgen receptor signaling and androgen-induced cell proliferation. [Isoform 1]: Isoform 1 and isoform 4 have different affinities for different nuclear receptors. [Isoform 4]: Isoform 1 and isoform 4 have different affinities for different nuclear receptors.
Synonyms: N-CoR2; SMRT; CTG26; SMRTE; TRAC-1; TNRC14; SMAP270; SMRTE-tau; TRAC1
Tractability: Small molecule: a structure with a bound ligand is known; a high-quality ligand is known; it belongs to a druggable protein family. PROTAC: UniProt records ubiquitination sites on it; ubiquitination databases record sites on it; its protein half-life has been measured; a small molecule that binds it is known.
Chemical probes: PD134120, PD134121, PD134122, PD134123
Safety:
Unwanted effects reported when the protein is acted on. In parentheses: how it was acted on, where the effect was seen, and who reports it.
Decreased, Body Weight (source: AOP-Wiki)
Gene: Protein-coding gene on chromosome 12 (124,324,407 to 124,567,623, reverse strand). Ensembl gene ENSG00000196498.
Subcellular location: Nucleus
Subcellular location (Human Protein Atlas): Nucleoplasm
Pathways (Reactome):
Disease: Constitutive Signaling by NOTCH1 HD+PEST Domain Mutants; Constitutive Signaling by NOTCH1 PEST Domain Mutants; HCMV Early Events
Gene expression (Transcription): MLL4 and MLL3 complexes regulate expression of PPARG target genes in adipogenesis and hepatic steatosis; Notch-HLH transcription pathway; Nuclear Receptor transcription pathway
Signal Transduction: Downregulation of SMAD2/3:SMAD4 transcriptional activity; NOTCH1 Intracellular Domain Regulates Transcription; NR1H2 & NR1H3 regulate gene expression to control bile acid homeostasis; NR1H3 & NR1H2 regulate gene expression linked to cholesterol transport and efflux
Developmental Biology: Differentiation of naive CD4+ T cells to T helper 2 cells (Th2 cells); Transcriptional regulation of white adipocyte differentiation
Metabolism: PPARA activates gene expression; Regulation of lipid metabolism by PPARalpha
Cellular responses to stimuli: Cytoprotection by HMOX1
Chromatin organization: HDACs deacetylate histones
Metabolism of proteins: SUMOylation of transcription cofactors
Gene Ontology:
Molecular function: enzyme activator activity; histone deacetylase binding; Notch binding; protein binding; transcription corepressor activity; chromatin binding; nuclear glucocorticoid receptor binding; nuclear receptor binding; nuclear retinoic acid receptor binding; nuclear retinoid X receptor binding; protein-containing complex binding
Biological process: negative regulation of androgen receptor signaling pathway; negative regulation of DNA-templated transcription; negative regulation of miRNA transcription; negative regulation of transcription by RNA polymerase II; regulation of ketone metabolic process; negative regulation of transcription initiation by RNA polymerase II; cerebellum development; estrous cycle; lactation; response to estradiol
Cellular component: chromatin; membrane; nuclear body; nuclear matrix; nucleoplasm; nucleus; transcription repressor complex; protein-containing complex
Genetic constraint (gnomAD): Loss-of-function variants: 83 observed, 222.34 expected, observed/expected ratio (o/e) 0.37, 90% interval 0.31 to 0.45. The synonymous counts are far from expectation, so gnomAD's model fits this gene poorly and the ratio says little. Missense variants: 3,361 observed, 3,241.4 expected, observed/expected ratio (o/e) 1.04, 90% interval 1.01 to 1.07. Synonymous variants: 1,644 observed, 1,365.9 expected, observed/expected ratio (o/e) 1.2, 90% interval 1.15 to 1.25.
Cancer hallmarks: escaping programmed cell death (suppresses); genome instability and mutations (suppresses); escaping programmed cell death (promotes); suppression of growth (promotes)
Homologues: Orthologues: chimpanzee NCOR2 (99% identical), macaque NCOR2 (98% identical), dog NCOR2 (93% identical), pig NCOR2 (89% identical), mouse Ncor2 (87% identical), rat Ncor2 (87% identical), guinea pig NCOR2 (86% identical), tropical clawed frog ncor2 (61% identical), rabbit NCOR2 (51% identical), zebrafish ncor2 (51% identical), Caenorhabditis elegans gei-8 (13% identical). Paralogues in human: NCOR1 (41% identical).
Diseases named in the same sentence as NCOR2 in open-access papers:
NCOR2 is named in the same sentence as 112 diseases in open-access papers, as found by Europe PMC text mining. Sharing a sentence is not in itself a finding about the gene and the disease. The quoted sentences say what the papers report.
breast carcinoma (41 papers, 2009 to 2026). "The transcriptional co-repressor protein NCOR2, it has been proven to be associated with various metabolic related cancers such as breast cancer and prostate cancer." (PMID 38779100, 2024). "We previously identified BQ323636.1 (BQ), a novel splice variant of NCOR2, can robustly predict tamoxifen resistance in ER+ primary breast cancer." (PMID 33806019, 2021). "Previously, we identified BQ323636.1 (BQ), a novel splice variant of nuclear co-repressor NCOR2, which can robustly predict tamoxifen resistance in primary breast cancer." (PMID 32110852, 2020). "For example, consider nuclear corepressor 2 (NCOR2), which is a member of the same nuclear receptor super-family as ERα, and has been associated with early tumor recurrence in breast cancer." (PMID 27539783, 2016). "In this study, we observed nominally significant associations with only 2 variants and breast cancer risk (His52Arg in NCOR2 and Arg12His in CALCOCO1), which is in line with expectation based on the number of tests that were performed (2 of 40 = 5%)." (PMID 19183483, 2009). "Thus, we set out to identify novel single nucleotide polymorphisms (SNPs) within SRC-1 (NCoA1), SRC-3 (NCoA3, AIB1), NCoR (NCoR1), and SMRT (NCoR2), and test the most promising SNPs for associations with breast cancer risk." (PMID 20003447, 2009). "In addition, the dopamine receptor D5 gene (DRD5) was described to be involved in tumor growth inhibition via autophagic cell death, NCOR2 was described to be associated with drug resistance in breast cancers and CRISP3 was associated with prostate and ovarian cancers." (PMID 33400739, 2020). "Our group identified a novel splice variant of NCOR2, BQ323636.1 (BQ), and we confirmed its clinical significance in breast cancer, particularly that of endocrine resistance." (PMID 40940753, 2025). "This study elucidates the role of BQ323636.1 (BQ), a splice variant of NCOR2, in conferring doxorubicin (DOX) resistance in ER+ breast cancer through an AR-dependent mechanism." (PMID 40940753, 2025). "By interacting with other co-repressing proteins, NCOR2 was identified as a fundamental modulator of the estrogen receptor in breast cancer patients treated with tamoxifen as adjuvant antihormonal therapy." (PMID 37131060, 2023). "PCR and subsequent agarose gel electrophoresis (AGE) results showed that AEP/tDDX3X-C enhanced the ES of PRDM2 exon 2, ARRB1 exon 13, and NCOR2 exon 21 in both glioma and breast cancer cells." (PMID 37988165, 2023). "In breast cancer cells, NCOR2 was proposed as a candidate to initiate cancer cell growth by modifying the transcriptional activity of ERα or directly influencing the ERα expression." (PMID 37131060, 2023). "Our previous studies identified a novel splice isoform of NCOR2, called BQ323636.1 (BQ), which is associated with TAM resistance in ER +ve breast cancer." (PMID 37190199, 2023). "High NCOR2 in the tumors of patients with breast cancer predicted chemotherapy refractoriness, tumor recurrence, and poor prognosis." (PMID 37512088, 2023). "Our findings suggest BQ can regulate the NRF2 signaling pathway via interference with NCOR2 suppressive activity and reveals a novel role for BQ as a modulator of chemoresistance in breast cancer." (PMID 32110852, 2020). "Our group has previously identified a novel splice variant of NCOR2, BQ323636.1 (called BQ in short) from SpliceArray profiling of breast cancer." (PMID 32110852, 2020). "Studies have shown that down-regulation of NCOR2 enhances the invasive ability of breast cancer cells and increase the growth and metastasis of breast cancer tumors in nude mice." (PMID 32508530, 2020). "Elevated levels of NCOR2 have been detected in breast cancer and prostate cancer, promoting cancer progression by suppressing vitamin D3 receptor (VDR) responsiveness 59-61." (PMID 32550907, 2020).
breast carcinoma (continued). "Our study provides evidence to support the idea that BQ can induce chemoresistance in breast cancer by altering the transcriptional suppressive function of NCOR2 on NRF2." (PMID 32110852, 2020). "For example, NCoR2 was described as a marker of earlier recurrence and poor outcome in breast carcinoma patients." (PMID 29470550, 2018). "Although NCOR2 was related to breast cancer, this regulation was only observed in a single tumor sample." (PMID 29207666, 2017). "Similar roles for NCOR1 and NCOR2/SMRT appear in the development of breast cancer and Tamoxifen resistance." (PMID 23098689, 2013). "We also identified three known poly-glutamine repeat polymorphisms, one in exon 20 of NCOA3., one in exon 15 of NCOR2., and one in exon 4 of SMARCA2; associations with these repeat polymorphisms and breast cancer risk will be examined in future studies." (PMID 19183483, 2009). "Preliminary analyses in a subset of 120 patients for whom the molecular breast cancer subtype was known suggest that NCOR2 and CITED2 mRNA levels are particularly prognostic in patients with luminal A tumours, but not luminal B tumours (data not shown)." (PMID 19904269, 2009). "It is noteworthy that the association of high NCOR2 levels with a favourable outcome in breast cancer patients seems to be in conflict with our cell line data, which showed increased NCOR2 mRNA and protein levels in tamoxifen-resistant cell lines." (PMID 19904269, 2009). "In ER +ve breast cancer, NCOR2 represses the activity of ER." (PMID 37190199, 2023). "Previous studies suggested that decreased NCOR2 expression promotes breast cancer initiation and progression by acting as a corepressor of estrogen receptor (ER), which has been shown to play an important role in the growth of breast cancer." (PMID 35646694, 2022). "We first confirmed that NCOR2 could form a protein complex with p50–p65 in breast cancer cells as shown by co-immunoprecipitation and next demonstrated that BQ could compromise the interaction between NCOR2 and p50–p65." (PMID 33806019, 2021). "Thus, we found that emodin performed the anti-angiogenesis function in breast cancer through modulating NCOR2 activity on SerRS promoter." (PMID 32550907, 2020). "On the contrary, NCoR2 reduced apoptosis in breast cancer cell lines." (PMID 29470550, 2018). "In the present study, NCOR2 enhancer methylation was significantly higher in the poor (non-relapse-free) prognosis patients, compared with the good (relapse-free) prognosis primary luminal A breast cancer patients." (PMID 26169690, 2015). "In trastuzumab-treated breast cancer cells NCOR2/SMRT interacts with MYC." (PMID 26117541, 2015). "Importantly, our experiments have shown that NCOR2, CITED2 and other genes previously revealed through functional screening are implicated in breast cancer outcome and therefore bear clinical relevance." (PMID 19904269, 2009). "Because of the critical importance of coregulators for ERα function, we hypothesized that breast cancer risk is influenced by SNPs within the coactivators SRC-1/NCoA1 and SRC-3/NCoA3/AIB1 and the corepressors NCoR and SMRT/NCoR2." (PMID 20003447, 2009). "The associations of NCOR2 and CITED2 with outcome in oestrogen receptor-positive breast cancer patients underscore the clinical relevance of functional genetic screens to better understand disease progression, which may ultimately lead to the development of improved treatment options." (PMID 19904269, 2009). "The genetic signaling pathway initiated by BQ overexpression, which disrupts the NCOR2–PPARγ interaction to de-repress ACSL4, positions BQ as a transcriptional hub in breast cancer." (PMID 40507798, 2025). "Comparing our findings of an ER interactome with those previously reported in ER+ breast cancer cells, only three ER interactors were common to all studies (NCOA3, NCOR2, and TRIM33)." (PMID 38473207, 2024).
breast carcinoma (continued). "Western blot was used to determine the expression levels of BQ and NCOR2 in the MCF-7 EpiR, MCF-7 TaxR and parental MCF-7 breast cancer cells." (PMID 32110852, 2020). "And in estrogen receptor alpha (ERα) positive breast cancer, YAP upregulates vestigial like family member 3 (VGLL3), recruiting the nuclear receptor co-repressor (NCOR2/SMRT) repressor to the estrogen receptor 1 (ESR1) super-enhancer, thereby silencing ERα transcription and inhibiting tumor growth." (PMID 40673277, 2025). "In an organoid-based study of breast cancer, the use of adenovirus to block the interaction of HDAC3 with nuclear receptor co-repressor 2 (NCOR2) was found to up-regulate the expression of interferon regulatory factor 1 (IRF-1) and interferon-γ (IFN-γ) factors." (PMID 40006729, 2025). "We hypothesized that BQ overexpression, by compromising the repressor activity of NCOR2, would enhance the activities of both ERE and ARE in breast cancer, conferring resistance to tamoxifen." (PMID 35054486, 2022). "In addition to finding previously well-known drivers, the identified modules pointed to other novel findings such as the interaction between NCOR2 and NCOA3 in breast cancer." (PMID 29023534, 2017). "Furthermore the ability of steroidal nuclear receptor such as the AR and ERα to bind NCOR1 and NCOR2/SMRT is important to therapeutic exploitation with receptor antagonists in prostate and breast cancer." (PMID 23098689, 2013). "As viral integrations in both NCOR2 and CITED2 yielded differences in gene expression patterns in our cell model, we quantified their mRNA levels in breast cancer tissues to further investigate the role of these two genes in tumour aggressiveness and resistance to tamoxifen." (PMID 19904269, 2009). "As NCOR2 is a transcriptional co-repressor gene, this finding suggests that BQ overexpression competes with NCOR2 to diminish the repression of ACSL4, leading to its upregulation, outlining the mechanism through which BQ modulates ACSL4 expression in breast cancer." (PMID 40507798, 2025). "However, apart from SMRT (NCOR2) and NR4A1 (both on 12q24 and showing increased gain in pure DCIS and increased loss in mixed DCIS), none of the genes has been associated with breast cancer in other studies." (PMID 26078038, 2015).
prostate carcinoma (20 papers, 2007 to 2025). A carcinoma that arises from epithelial cells of the prostate gland. "Reduced expression of NCOR2 has been associated with disease aggressiveness in prostate cancer, and knockdown of NCOR2 in cell line models leads to neuroendocrine prostate cancer (NEPC) gene signatures." (PMID 38379333, 2024). "In prostate cancer, loss of the repressive function of NCOR2 altered the AR response to ligands and contributed to cancer development." (PMID 37131060, 2023). "We observed enrichment of mutations in several genes including understudied genes such as EYA1, CSMD3, FLT4, NCOR2, and PCDH15 and found that mutations in EYA1 and CSMD3 are associated with a poor outcome in prostate cancer." (PMID 38067373, 2023). "Recently, it has been shown that reduced NCOR2 expression accelerates failure of androgen deprivation therapy in prostate cancer patients." (PMID 38067373, 2023). "In more advanced type of prostate cancer (MCRPC), splice-disrupt variants, located on CDs of NCOR2, PTPRC, and CRP, are the high-risk variants." (PMID 35286517, 2022). "Elevated NCOR2 levels are common in prostate cancer cells, resulting in promoting cell proliferation." (PMID 36497280, 2022). "Upregulation of DUB3 induced by nuclear receptor corepressor 2 (NCOR2) gene deletion in prostate cancer leads to BET inhibitor resistance resulting from elevated BRD4, which converges with SPOP mutation." (PMID 31311566, 2019). "NCOR2 is also differentially expressed in bladder, breast, and prostate cancers." (PMID 30709419, 2019). "Resistance rooted from SPOP mutations and NCOR2 deficiency appears cancer-type specific to prostate cancer because SPOP mutations in endometrial cancer sensitize BET inhibitor, an effect converse in prostate cancer." (PMID 31311566, 2019). "The presence of mutations in two additional tumors (track 3) as well as another case of translocation (track 4), further supports the hypothesis that the NCOR2 gene is relevant for prostate cancer biology." (PMID 24684958, 2014). "We did not include the genes whose expression is not correlated with the associated category e.g. NCOR2 gene suppresses tumor growth in prostate cancer cells but is up-regulated in RCC, and hence it is not included." (PMID 19455236, 2007). "Expression profiling in solid tumors has revealed altered NCOR1 and NCOR2/SMRT expression and localization, for example in breast, bladder, and prostate cancers." (PMID 23098689, 2013).
lymphoma (7 papers, 2014 to 2025). A malignant (clonal) proliferation of B- lymphocytes or T- lymphocytes which involves the lymph nodes, bone marrow and/or extranodal sites. "We have also described the presence of LoF variants in the genes CR1, IBTK, and NCOR2 that have been related to B cell development and activation, agammaglobulinemia, and lymphoma, respectively." (PMID 29867916, 2018). "In our results, some of the differentially methylated genes in EHMT2 + MCL cases have also been reported with recurrent genetic alterations in lymphoma, such as ALK, DUSP22, NCOR2, RORA, DLC1, JAG1/2, JAK1, NOTCH4, and CD1938–45." (PMID 34633777, 2021). "However, the panel targeted the most relevant genes for lymphoma diagnosis but did not cover all exons for some genes (e.g., KMT2D) and lacked a few select genes (e.g., FAS, SLAMF1, SPEN, and NCOR2), which are described in cutaneous MZL10,32." (PMID 37081015, 2023).